FBXO25 (F-box protein 25)
Description:
Substrate-recognition component of the SCF (SKP1-CUL1-F-box protein)-type E3 ubiquitin ligase complex. May play a role in accumulation of expanded polyglutamine (polyQ) protein huntingtin (HTT) (By similarity).
Synonyms: FBX25
Tractability: PROTAC: ubiquitination databases record sites on it.
Gene: Protein-coding gene on chromosome 8 (406,428 to 477,967, forward strand). Ensembl gene ENSG00000147364.
Subcellular location: Nucleus
Gene Ontology:
Molecular function: ubiquitin-protein transferase activity
Biological process: protein ubiquitination; SCF-dependent proteasomal ubiquitin-dependent protein catabolic process
Cellular component: nucleolus; nucleus; cytoplasm; SCF ubiquitin ligase complex; ubiquitin ligase complex
Genetic constraint (gnomAD): Loss-of-function variants: 32 observed, 32.9 expected, observed/expected ratio (o/e) 0.97, 90% interval 0.73 to 1.31. The synonymous counts are far from expectation, so gnomAD's model fits this gene poorly and the ratio says little. Missense variants: 391 observed, 319.45 expected, observed/expected ratio (o/e) 1.22, 90% interval 1.13 to 1.33. Synonymous variants: 170 observed, 119.43 expected, observed/expected ratio (o/e) 1.42, 90% interval 1.26 to 1.62.
Homologues: Orthologues: chimpanzee FBXO25 (99% identical), macaque FBXO25 (99% identical), pig FBXO25 (93% identical), guinea pig FBXO25 (93% identical), dog FBXO25 (92% identical), rat Fbxo25 (89% identical), mouse Fbxo25 (88% identical), rabbit FBXO25 (83% identical), zebrafish fbxo25 (77% identical), tropical clawed frog fbxo25 (70% identical), Caenorhabditis elegans mfb-1 (28% identical), Drosophila melanogaster CG11658 (27% identical). Paralogues in human: FBXO32 (61% identical).
Diseases named in the same sentence as FBXO25 in open-access papers:
FBXO25 is named in the same sentence as 11 diseases in open-access papers, as found by Europe PMC text mining. Sharing a sentence is not in itself a finding about the gene and the disease. The quoted sentences say what the papers report.
cardiac hypertrophy (1 paper, 2023). "As a proof-of-principle, we evaluated the Fbxo25 in different models: neonatal cardiomyocytes, and in vivo model of pathologic cardiac hypertrophy upon transverse aortic constriction." (PMID 36969608, 2023). "Therefore, Fbxo25 might display a counteractive regulation in heart hypertrophy." (PMID 36969608, 2023). "Therefore, our study suggests yet unknown UPS subunits to play a potential role in cardiac hypertrophy, however due to our experimental design, our results can’t assign our screening hits, e.g., Fbxo25 to either physiological or pathophysiological cardiac hypertrophy." (PMID 36969608, 2023).
epilepsy (1 paper, 2021). A brain disorder characterized by episodes of abnormally increased neuronal discharge resulting in transient episodes of sensory or motor neurological dysfunction, or psychic dysfunction. "Examples are CSMD1 in 8p23.2, a dosage-sensitive gene associated to ASD, schizophrenia and epilepsy and FBXO25, recently associated to neuropsychiatric disorders." (PMID 33925474, 2021).
tumor (5 papers, 2016 to 2025). "ACTN1, upregulated in OC and linked to poor prognosis, promotes tumor growth, EMT, and M2 macrophage polarization via ERK1/2 signaling; FBXO25 interacts upstream, and ERK1/2 inhibition partially reverses these effects." (PMID 41280929, 2025).
cancer (2 papers, 2020 to 2022). A tumor composed of atypical neoplastic, often pleomorphic cells that invade other tissues. "Common CNLs negatively influencing DFS and cancer-specific OS harboured the feline orthologous of multiple HBC-related genes reported as commonly deleted including FOXP1, FBXO25, CSMD1, AGPAT5, PCM1, PTPRG, and PDGFRL15,19,27,28,41–43." (PMID 31969654, 2020).
cardiac diseases (1 paper, 2023). "Besides Atrogin-1 (Fbxo32) and Fbxo25, published data about the role of the F-box proteins in cardiac diseases and growth control is still rare." (PMID 36969608, 2023).
infection (1 paper, 2014). The state of being infected such as from the introduction of a foreign agent such as serum, vaccine, antigenic substance or organism. "Infection of shRNAs against eight F-box proteins (FBXL5, FBXW5, FBXO3, FBXO4, FBXO5, FBXO24, FBXO25 and FBXO27) upregulated Snail1 protein levels (at least by 2-fold) compared with parental cells or cells infected with a control shRNA." (PMID 24157836, 2014).
FBXO25 also shares sentences with these, for which no sentence is quoted: B-cell CLL (1 paper); cardiovascular diseases (1); chlamydia (1); neurological diseases (1); schizophrenia (1).